FGF23 (fibroblast growth factor 23)
Diseases named in the same sentence as FGF23 in open-access papers (continued):
Sharing a sentence is not in itself a finding about the gene and the disease.
End Stage Liver Disease (4 papers, 2013 to 2025). Final stage of a liver disease when the liver failure is irreversible and LIVER TRANSPLANTATION is needed. "In this study we report for the first time that plasma FGF23 concentration is increased in patients with end stage liver disease and we show that FGF23 plasma levels predict the risk of death in patients on the liver-transplant waiting list." (PMID 23825530, 2013). "FGF23 may similarly increase the risk of death in patients with end stage liver disease." (PMID 23825530, 2013). "We measured plasma FGF23 concentration in 200 patients with end stage liver disease at the time when they were considered as eligible for liver transplantation." (PMID 23825530, 2013). "In conclusion we report that plasma FGF23 concentration is increased in patients with end stage liver disease on a waiting list for liver transplantation and is markedly associated with an increased risk of mortality." (PMID 23825530, 2013). "In patients with end stage liver disease, FGF23 is increased owing to hepatic FGF23 production." (PMID 35084563, 2022). "The aim of this study was to determine if plasma FGF23 concentration could be modified in end stage liver disease and the consequences of these modifications." (PMID 23825530, 2013). "We checked if FGF23 concentration could be modified in patients with end stage liver disease (ESLD) and predict mortality." (PMID 23825530, 2013).
endometrial cancer (4 papers, 2020 to 2023). Primary or metastatic malignant neoplasm involving the endometrium (mucous membrane that lines the endometrial cavity). "FGF21 and FGF23 expression have been implicated in endometrial cancer due to their association with increased expression of leptin (LEP), a hormone produced in adipose tissue." (PMID 34068954, 2021). "In our study we assessed role of FGF21 and FGF23 in the diagnostics of patients with endometrial cancer." (PMID 32570721, 2020). "To date, no direct relationship has been identified between the overexpression of FGF23 and the pathogenesis of endometrial cancer." (PMID 32570721, 2020). "It appears that as of this day, FGF23 cannot be used in the diagnostics or prognostics of endometrial cancer." (PMID 32570721, 2020). "Although not directly linked to the SNP, FGF23 overexpression has also been associated with reduced overall survival and shortened time to occurrence of bone metastases A large proportion of endometrial cancers are associated with metabolic disorders, including obesity." (PMID 34068954, 2021). "In our study, we observed significantly higher levels of leptin and FGF21, but not of FGF23, in overweight and obese patients with endometrial cancer." (PMID 32570721, 2020). "In our studies, a strong correlation was observed between the FGF23 and leptin hormone levels, while no statistically significant increase in the levels of FGF23 was observed in obese patients with endometrial cancer." (PMID 32570721, 2020).
hereditary hypophosphatemic rickets with hypercalciuria (4 papers, 2010 to 2026). Hereditary hypophosphatemic rickets with hypercalciuria (HHRH) is a hereditary renal phosphate-wasting disorder characterized by hypophosphatemia and hypercalciuria associated with rickets and/or osteomalacia. "A key exception to the rule is hereditary hypophosphatemic rickets with hypercalciuria (HHRH) in which patients show suppressed or low-normal FGF23 levels." (PMID 30808384, 2019).
hyperaldosteronism (4 papers, 2018 to 2025). Overproduction of aldosterone by the adrenal glands, which may lead to hypokalemia and/or hypernatremia. "Mineralocorticoid receptor agonists including aldosterone induce the synthesis of FGF23, as seen in primary and secondary hyperaldosteronism." (PMID 33517471, 2021). "Experiments with the mineralocorticoid receptor blocker eplerenone furthermore suggest that the observed increase in FGF23 levels in NCC KO mice is primarily a result of the volume depletion-induced secondary hyperaldosteronism." (PMID 29483574, 2018). "However, we found hypernatremia in TAC mice, possibly due to hyperaldosteronism and/or increased FGF23 levels." (PMID 41515999, 2025).
hyperkalaemia (4 papers, 2014 to 2025). "Serum potassium remained unchanged in Kl−/−/VDRΔ/Δ and was actually lower in Fgf23−/−/VDRΔ/Δ compared with wild-type and VDRΔ/Δ mice, ruling out hyperkalemia as the driving force for increased aldosterone secretion in compound mutant mice." (PMID 24797667, 2014).
hypogonadism (4 papers, 2021 to 2025). A disorder characterized by decreased function of the gonads. "Fgf23-/- mice exhibit hypogonadism and spermatogenic arrest, which resembles the condition of some men with testicular dysgenesis syndrome that occasionally have testicular microcalcifications despite no malignancy." (PMID 40279260, 2025). "An animal experiment confirmed that mice with FGF23 gene ablation showed short life, kyphosis, and hypogonadism." (PMID 37644169, 2023).
idiopathic pulmonary fibrosis (4 papers, 2022 to 2025). Idiopathic pulmonary fibrosis (IPF) is a nonneoplastic pulmonary disease that is characterized by the formation of scar tissue within the lungs in the absence of any known cause. "In a similar beneficial role, circulating and pulmonary FGF23 levels are elevated in patients with idiopathic pulmonary fibrosis, but FGF23 itself did not cause the upregulation of fibrotic genes in pulmonary fibroblasts." (PMID 37763754, 2023).
injury (4 papers, 2022 to 2024). Damage inflicted on the body as the direct or indirect result of an external force, with or without disruption of structural continuity. "It will be interesting to know if there exists a CBIR-ERRγ-FGF23 axis in alcohol-induced liver injury." (PMID 38479224, 2024). "In this study, we report that carbon tetrachloride (CCl4)-induced acute liver injury upregulates hepatic estrogen-related receptor gamma (ERRγ) and FGF23 gene expression and FGF23 secretion from liver." (PMID 37396546, 2023). "Glomerular overexpression of VCAM-1 and E-selectin induces the recruitment of Mac-1/podoplanin-positive macrophages, leading to the deposition of unmetabolized angiotensin-converting enzyme 2 (ACE2) and fibroblast growth factor 23 (FGF23) and inflammation-induced kidney injury in diabetics." (PMID 36430760, 2022). "Thus, we hypothesized that targeting downstream signaling steps with SIK inhibitors might induce 1,25-vitamin D stimulation, even in the setting of early-stage kidney injury, by bypassing defects due to PTH receptor downregulation and high serum levels of FGF23." (PMID 36862513, 2023).
ischemic stroke (4 papers, 2020 to 2025). A stroke disorder caused by obstruction of blood flow to the brain, due to thrombotic (local blood clot formation) or embolic (due to a blood clot or other material traveling from another site) event. "This pilot study suggest the potential of FGF-23 as a valuable marker for neovascularization and atherosclerotic carotid plaque instability as a risk factor for ischemic stroke." (PMID 38711510, 2024). "MR was applied to infer the causality of FGF23 levels and the risk of ischemic stroke using data from the MEGASTROKE consortium." (PMID 33424930, 2020). "In this study, we aimed to assess the association of FGF23 with ischemic stroke and its subtypes by applying a Mendelian randomization (MR) framework." (PMID 33424930, 2020). "However, serum levels of FGF-23 have also been associated with a higher risk of cardiovascular disease (CVD), such as myocardial infarction, ischemic stroke, and heart failure, and these associations were not restricted to patients with impaired kidney function." (PMID 38711510, 2024).
periodontitis (4 papers, 2021 to 2025). An acute or chronic inflammatory process that affects the tissues that surround and support the teeth. "We also aim to determine the association between FGF23, calcium, phosphate, iPTH, creatinine, urea, plaque score, and bleeding score with the presence of periodontitis in predialysis CKD patients." (PMID 39176315, 2024). "Additionally, associations between FGF23, calcium, phosphate, iPTH, creatinine, urea, plaque score, and bleeding score with periodontitis in CKD patients were determined." (PMID 39176315, 2024). "Since both FGF23 and periodontitis are linked to inflammatory processes, investigating their interplay could uncover new pathways of inflammation-driven CKD progression." (PMID 39176315, 2024). "Increased unmetabolized FGF23 in the kidney and blood would provide a prediction of proteinuria in diabetic patients with periodontitis." (PMID 40421989, 2025). "Periodontitis, a condition recognized as a risk factor for CKD, is also potentially associated with the increment of FGF23." (PMID 39176315, 2024). "If periodontitis is found to significantly influence FGF23 levels and subsequently CKD progression, it could present a novel therapeutic target for improving outcomes in CKD patients." (PMID 39176315, 2024). "The lack of significant difference in FGF23 levels in this study may suggest that the presence of CKD and its associated mechanisms of elevated FGF23 might overshadow the impact of periodontitis on FGF23 levels." (PMID 39176315, 2024). "Emerging studies suggest a relationship between periodontitis and elevated FGF23 levels." (PMID 39176315, 2024). "However, the specific contribution of periodontitis to increased FGF23 levels in CKD patients remains unclear due to limited research on this subject." (PMID 39176315, 2024). "Thus far, there is no comparable literature associating FGF23 in CKD patients with periodontitis." (PMID 39176315, 2024). "This suggests that periodontitis does not significantly alter the interactions between FGF23 and these analytes." (PMID 39176315, 2024). "Future research should explore the impact of periodontitis severity on FGF23 levels and consider longitudinal studies to assess whether treating periodontitis in CKD patients has any long-term benefits on FGF23 levels and overall CKD outcomes." (PMID 39176315, 2024). "While our findings indicate that periodontitis does not significantly influence the relationship between FGF23, calcium, phosphate, and iPTH, it remains crucial to consider the broader implications of chronic inflammation on CKD progression." (PMID 39176315, 2024). "The study suggests that while periodontitis treatment may not significantly impact FGF23 levels in CKD patients, the potential role of periodontal health in managing overall CKD progression and complications should not be overlooked." (PMID 39176315, 2024). "Changes in FGF23, calcium, phosphate, iPTH, creatinine, urea, and plaque score could not be attributed to the presence of periodontitis in CKD patients." (PMID 39176315, 2024). "Moreover, the presence of periodontitis does not influence the relationship between calcium, phosphate, iPTH, and FGF23." (PMID 39176315, 2024). "Additionally, the impact of periodontitis on systemic inflammation might not reach the threshold needed to affect FGF23 and its related pathways significantly." (PMID 39176315, 2024). "This study aims to compare FGF23 levels in CKD patients with and without periodontitis and non-CKD patients with and without periodontitis." (PMID 39176315, 2024). "This study aims to compare the level of FGF23 in predialysis CKD patients with periodontitis, predialysis CKD patients without periodontitis, periodontitis patients without CKD, and healthy population and determine their correlation with phosphate, calcium, and intact parathyroid hormone (iPTH)." (PMID 39176315, 2024).
preeclampsia (4 papers, 2024 to 2025). Preeclampsia is a hypertensive disorder of pregnancy that is characterized by new-onset hypertension with proteinuria presenting after 20 weeks of gestation, and depending on mild or severe forms may initially present with severe headache, visual disturbances, and hyperreflexia. "In contrast, serum FGF-23 and calcium concentrations were significantly lower in patients with gestational hypertension and FGR compared to the control group (p = 0.044 and p < 0.001)." (PMID 40648894, 2025). "The authors of another study analysed serum FGF-23 levels in women with gestational hypertension and in healthy pregnant women and assessed the presence of fetal growth disorders." (PMID 40648894, 2025). "Zhao and colleagues studied serum fibroblast growth factor 23 (FGF23) in healthy women or pregnant women with preeclampsia and examined its role mediating placental angiogenesis through ERK1/2-EGR1 signaling." (PMID 39619154, 2024). "The objective of this study was to determine serum fibroblast growth factor-23 levels in preeclampsia, eclampsia, gestational hypertension, and the presence of fetal growth restriction subgroups." (PMID 39045952, 2024). "'s studies suggest a potential mechanism in the development of preeclampsia, future studies should determine if FGF23 levels correlate with preeclampsia severity or if the FGF23-ERK1/2-EGR-1 pathway is causal for preeclampsia in animal models." (PMID 39619154, 2024). "The aim of this study was to determine the levels of serum FGF23 in pregnancies complicated with GHD and investigate FGF23 levels in preeclampsia, eclampsia, GHT, and the presence of fetal growth restriction (FGR) subgroups." (PMID 39045952, 2024). "The evaluation of the role of FGF-23 has shown that its low level could be related to gestational hypertension and fetal growth restriction." (PMID 40648894, 2025). "They found that third trimester FGF23 levels were lower in women with preeclampsia." (PMID 39619154, 2024). "According to the Evaluation of maternal serum fibroblast growth factor-23 levels in FGR and gestational hypertensive disease study, FGF-23 plays an important role in the pathogenesis of gestational hypertension and fetal growth disorders." (PMID 40648894, 2025). "In the study group (with and without FGR), serum FGF-23 values in women with gestational hypertension and without FGR were found to be similar to the results in the control group." (PMID 40648894, 2025). "In the only study included in our review, no overall differences in FGF-23 levels were found, when comparing women with gestational hypertension with healthy pregnant women." (PMID 40648894, 2025). "The lower levels of FGF-23 and calcium in patients with FGR and gestational hypertension suggest a possible dysfunction of the electrolyte axis, which may contribute to fetal growth abnormalities." (PMID 40648894, 2025). "All the studies discussed suggest that FGF-21, FGF-19 and FGF-23 may play an important role in fetal and neonatal growth and development, particularly in pregnancies complicated by metabolic disorders, such as GDM or gestational hypertension." (PMID 40648894, 2025).
Proteinuria (4 papers, 2012 to 2025). Increased levels of protein in the urine. "Proteinuria is also reported associated with increased circulation levels of FGF23, a core regulator of phosphate metabolism." (PMID 40421989, 2025). "Proteinuria induces elevation of both plasma phosphate and FGF23 concentrations independent of GFR and it is controversial whether, for a similar degree of GFR reduction, patients with glomerular diseases have higher serum levels of FGF23 than those with CKD caused by other nephropathies." (PMID 37047636, 2023).
Renal cyst (4 papers, 2014 to 2024). A fluid filled sac in the kidney. "Some scholars believe that fibroblast growth factor 23 (FGF23) plays a significant role in the development of cystic kidney disease." (PMID 39346645, 2024). "So, FGF23 might be a key point in the relationship between vitamin D levels and cystic kidney disease." (PMID 39346645, 2024). "FGF23 protein has been detected in cells lining renal cysts in rodent models of PKD." (PMID 29518087, 2018). "Alternatively, FGF23 mRNA and protein expression was detected in cell lining renal cysts, but not in bone of the cy/+ Han:SPRD rat model of PKD; similar finding was also observed in an inducible Pkd1 knockout mouse model, suggesting ectopic expression of FGF23 in CKD." (PMID 25464512, 2014).
X-linked dominant hypophosphatemic rickets (4 papers, 2009 to 2023). "An elevated FGF-23 level can be observed in distinct hereditary disorders including X-linked vitamin D-resistant rickets, as well as in association with cardiovascular disease and bone-related cancer." (PMID 37432176, 2023).
Acidosis (3 papers, 2016 to 2025). Abnormal acid accumulation or depletion of base. "The favorable effect of exercise on serum concentrations of Klotho and FGF-23 may be related to better control of oxidative stress, chronic inflammation and metabolic acidosis that develops as a result of energy wasting." (PMID 38169578, 2024).
Arthritis (3 papers, 2023 to 2025). Inflammation of a joint. "A significant correlation was also observed between the concentrations of FGF-22 and FGF-23 and arthritis (p = 0.01; p = 0.02)." (PMID 40943671, 2025). "Recent studies have increasingly illuminated the relationship between FGF23 and arthritis, with evidence suggesting that FGF23 enhances the expression of ColX, MMP13, and MMP9 in chondrocytes through the modulation of the Wnt/β-catenin signaling pathway, ultimately contributing to OA." (PMID 40538811, 2025).
bone metastasis (3 papers, 2023 to 2024). Transfer of a neoplasm from its primary site to bones. "In patients with bone metastasis due to different solid tumours, a higher FGF23 plasma concentration is associated with shorter survival and shorter time to skeletal-related events." (PMID 38397231, 2024). "For example, it has been reported that higher levels of FGF23 in patients with bone metastasis from various solid tumors correlate with decreased survival and shorter time to skeletal-related events." (PMID 38806758, 2024). "In patients with cancer and bone metastases from solid tumors, elevated serum levels of FGF23 were associated with shorter survival, as well as time to skeletal-related events, providing the first evidence of the prognostic significance of FGF23 in individuals with bone metastasis." (PMID 36926025, 2023).
cerebral small vessel disease (3 papers, 2017 to 2019). Cerebral small vessel disease is the term currently used to pathological processes that affect the brain parenchymal circulation (arterioles, capillaries, and veins). "Fibroblast growth factor 23 is an emerging vascular biomarker, recently associated with cerebral small vessel disease and poor cognition in patients on dialysis." (PMID 30830941, 2019). "In addition, higher FGF23 levels have been associated cross-sectionally with radiographic markers of cerebral small vessel disease as well as with poor cognitive performance in a small number of patients on hemodialysis." (PMID 30830941, 2019).
cerebrovascular disease (3 papers, 2020 to 2024). "Further research is needed to confirm the findings and investigate the potential therapeutic implications of targeting FGF23 in the prevention and treatment of cerebrovascular disease." (PMID 39096857, 2024). "Therefore, further research is needed to address these limitations in the investigation of the potential role of FGF23 in the diagnosis and treatment of cerebrovascular disease." (PMID 39096857, 2024). "Recent studies have also identified FGF23 as an independent risk factor for cerebrovascular diseases in both CKD and non-CKD populations." (PMID 34759797, 2021). "The FGF23/klotho axis is a key participant in CKD-MBD and is closely related to vascular calcification and cerebrovascular diseases." (PMID 34759797, 2021).